ZEB2 (zinc finger E-box binding homeobox 2)
Diseases named in the same sentence as ZEB2 in open-access papers (continued):
Sharing a sentence is not in itself a finding about the gene and the disease.
renal cell carcinoma (12 papers, 2013 to 2024). "The clinical data showed that the expression of METTL3 and ZEB2 in RFs was significantly greater than that in adjacent normal tissues from renal cell carcinoma patients." (PMID 39059495, 2024). "A previous study showed that elevated ZEB2 transcripts were detected in von Hippel-Lindau-null renal cell carcinomas in a hypoxia-inducible factor 1 alpha-dependent manner." (PMID 23658743, 2013). "The correlation between ZEB2 expression and epithelial-mesenchymal transition markers in renal cell carcinoma." (PMID 23658743, 2013). "However, the tumor suppressor role of miR-708 in renal cell carcinoma is mediated by reduced Survivin, Zinc finger E-box-binding homeobox 2 (ZEB2), and FLICE-like Inhibitory Protein (FLIP) targeting." (PMID 35011736, 2022). "However, the expression status of ZEB2 in renal cell carcinoma (RCC) and ZEB2’s clinicopathologic/prognostic significance are poorly understood." (PMID 23658743, 2013). "It has been demonstrated that ZEB2 expression promotes epithelial-to-mesenchymal transition (EMT) in renal cell carcinoma (RCC) and accumulated ZEB2 is an effective biomarker for the poor prognosis of patients with RCC." (PMID 32149094, 2020). "Other EMT regulators, such as Zeb1, Zeb2, and TCF-3, have been reported to be upregulated in pVHL-null renal cell carcinoma in which HIF-1α is constitutively overexpressed." (PMID 30696468, 2019). "Functional studies on miR-708 in renal cell carcinoma (RCC) showed that miR-708 was identified as target for survivin, Zinc finger E-box-binding homeobox 2 (ZEB2) and B lymphoma Mo-MLV insertion region 1 homolog (BMI1), and expression level of miR-708 was widely reduced in RCC patients." (PMID 30463333, 2018).
Intellectual disability (11 papers, 2013 to 2025). "The hallmark features include distinct dysmorphic facial features, developmental delay/intellectual disability and a pathogenic heterozygous variant in the ZEB2 gene or a full/partial deletion of chromosome 2q22.3, including the ZEB2 gene." (PMID 39941075, 2025). "In addition to ASCL1 and NEUROG2, other neurodevelopmental transcriptional regulators such as, MEF2C (syndromic mental retardation) and ZEB2 (MWS) were also differentially expressed in TCF4-depleted cells." (PMID 24058414, 2013).
microcephaly (11 papers, 2013 to 2025). A congenital or acquired developmental disorder in which the circumference of the head is smaller than normal for the person's age and sex. "ZFHX1B (ZEB2/SIP1) mutations cause HSCR in the context of Mowat-Wilson syndrome, which also includes microcephaly, mental retardation, and dysmorphic facial features." (PMID 23639815, 2013). "The abnormalities in craniofacial bone and teeth observed in Zeb2-cKO mice might be relevant to the characteristic microcephaly and frequently found malalignment of teeth in MOWS patients." (PMID 28422173, 2017).
endometriosis (10 papers, 2015 to 2025). The growth of functional endometrial tissue in anatomic sites outside the uterine body. "Studies in a mouse model of endometriosis further demonstrated that metastasis associated 1 (MTA1) and zinc finger E-box binding homeobox 2 (ZEB2) were up-regulated in ectopic tissues, while polyphenols inhibited ectopic lesion growth and MTA1/ZEB2 expression." (PMID 37375677, 2023). "Based on the accessible literature, higher ZEB2 expression has been observed in endometriotic tissue of patients with endometriosis." (PMID 36289723, 2022). "It is shown that miR-200b-3p contributes to the feedback regulation of EMT by downregulating ZEB1 and ZEB2 in endometriosis." (PMID 36289820, 2022). "Based on their findings, miR-200b-3p was linked to transcription factors such as DNA methyltransferase 1 (DNMT1), enhancer of zeste homolog 2 (EZH2), Hepatocyte nuclear factor-1-beta (HNF1B), MYB, JUN, ZEB1, and ZEB2 during endometriosis pathogenesis." (PMID 36289820, 2022). "A significant ZEB2 overexpression in endometriosis tissue samples was identified compared to levels detected in the normal endometrium." (PMID 36289723, 2022). "MALAT1 has been shown to induce EMT during endometriosis and metastasis in clear cell kidney carcinoma mouse models via the miR200/ZEB2 axis by acting as a sponge for the miR200 family." (PMID 34993023, 2021). "miR-200b-3p was associated with the transcription factors DNMT1, EZH2, HNF1B, JUN, MYB, ZEB1, and ZEB2 during the pathogenesis of endometriosis." (PMID 32802844, 2020). "Other studies showed that miR-200b-3p downregulates ZEB1 and ZEB2 in endometriosis patients and participates in the feedback regulation of EMT, which more easily promotes cell invasion and metastasis." (PMID 32802844, 2020). "Then, DNMT1, EZH2, HNF1B, JUN, MYB, ZEB1, and ZEB2 were found as TFs related to endometriosis by interacting with target genes of miR-200b-3p." (PMID 32802844, 2020). "Knowledge about ZEB2 involvement in endometriosis pathomechanism is much less advanced." (PMID 36289723, 2022). "miR-200c by targeting MALAT1/ZEB1/ZEB2 could suppress endometriosis." (PMID 32850438, 2020). "In another study, miRNA 200b was reported to play a role in the pathogenesis of endometriosis by regulating the stem cell phenotype, proliferation, and invasive extension formation in endometriotic cells by targeting ZEB1, ZEB2, and KLF4." (PMID 40572723, 2025). "Several studies have investigated the biological role of miR-200 family members in endometriosis and shown that these family members prevent EMT by suppressing ZEB1 and ZEB2 expression." (PMID 36289820, 2022). "We identified miR-200c as an EMT-suppressive miRNA in endometriosis that acts, at least in part, by downregulating the RNA level of MALAT1, which in turn functions as a ceRNA to upregulate ZEB1 and ZEB2 by sequestering miR-200c." (PMID 29116025, 2017). "Both ZEB1 and ZEB2 do not seem to have a significant value in the initial diagnosis of endometriosis as a single marker." (PMID 36289723, 2022). "The aim of this study was to compare levels of ZEB1 and ZEB2 in the peritoneal fluid and plasma between patients with and without endometriosis in order to assess their utility in the endometriosis diagnostic process." (PMID 36289723, 2022).
esophageal squamous cell carcinoma (10 papers, 2011 to 2024). Esophageal squamous cell carcinoma (ESCC) is a type of esophageal carcinoma (EC) that can affect any part of the esophagus, but is usually located in the upper or middle third. "ZEB2 was reported to negatively correlate with miR-205 levels in esophageal squamous cell carcinoma cells and silencing of ZEB2 lead to suppressed cell viability, migration, and invasion in laryngeal squamous cell carcinoma cells." (PMID 35223452, 2021). "For instance, ZEB1‐activated LBX2‐AS1 interplays with HNRNPC to strengthen the stability of ZEB1 and ZEB2 and promotes esophageal squamous cell carcinoma." (PMID 32871048, 2020). "Moreover, it has been proved that Zinc-finger E-box binding homeobox 1 (ZEB1) could induce upregulation of LBX2-AS1 to enhance the stability of ZEB1 and ZEB2, which could promote the migration and mesenchymal transformation of esophageal squamous cell carcinoma." (PMID 36313642, 2022). "In esophageal squamous cell carcinoma (ESCC) cell lines, TWIST1 is a crucial transcription factor that enhances the epithelial-mesenchymal transition (EMT) by downregulating E-cadherin and upregulating mesenchymal genes such as N-cadherin, ZEB2, vimentin, and fibronectin." (PMID 38589525, 2024).
clear cell kidney carcinoma (9 papers, 2015 to 2022). "In different human tumors, ZEB2 was found to regulate various miRNAs, such as miR-132, miR-101, miR-144, and miR-141.273, 274, 275, 276 In a recent study, MALAT1 was found to affect ZEB2 expression via sponging miR-200 in clear-cell renal carcinoma." (PMID 35071748, 2022).
serous ovarian cancer (9 papers, 2013 to 2025). "Another research reported that ZEB2 induces peritoneal metastasis of high-grade serous ovarian carcinoma." (PMID 40510028, 2025). "Research on ZEB2 in peritoneal metastatic cancer shows that ZEB2 promotes peritoneal metastasis of high-grade serous ovarian cancer by regulating cancer stem-like cells." (PMID 39247601, 2024). "In ovarian serous adenocarcinoma cells, the expression of VASH2 was inversely correlated with that of miR-200b, which represses the expression of ZEB1 and ZEB2, the products of which are key to epithelial-to-mesenchymal transition." (PMID 23426782, 2013).
acute myeloid leukemia (8 papers, 2015 to 2025). Acute myeloid leukemia (AML) is a group of neoplasms arising from precursor cells committed to the myeloid cell-line differentiation. "Further studies have found a higher ZEB2 expression in early T-cell precursor acute lymphoblastic leukemia (ETP-ALL) patients as compared to acute myeloid leukemia patients." (PMID 39941895, 2025). "However, ZEB2 expression was higher in acute myeloid leukemia (LAML), brain lower grade glioma (LGG), pancreatic adenocarcinoma (PAAD), and skin cutaneous melanoma (SKCM) than in normal tissue." (PMID 35723302, 2022). "Besides predictive modeling, the Achilles project has been instrumental in identifying ZEB2 as a novel dependency of Acute myeloid leukemia (AML), as well as 352 other genes which are essential specifically in AML." (PMID 36803845, 2023). "Finally, inactivation of Zeb2 alone or Zeb1/2 together was found to enhance survival in secondary MLL-AF9 acute myeloid leukemia (AML) models attesting to the oncogenic role of ZEB1/2 in AML." (PMID 34550965, 2021). "ZEB2 depletion significantly hinders the gene transcription that is involved in cell adhesion and migration and thus impair proliferation and EMT, both in human and in mouse acute myeloid leukemia cells." (PMID 32149094, 2020). "Within the myeloid lineage, however, there is emerging evidence that ZEB2 and ZEB1 may both potentially contribute to the development and/or maintenance of acute myeloid leukemia (AML)." (PMID 34550965, 2021).
breast tumors (8 papers, 2006 to 2025). "According to a previous study, ZEB1 and ZEB2 repress E-cadherin expression, whereas ZEB2 directly interacts with the vimentin promoter in human epithelial breast tumor cells." (PMID 41002590, 2025). "This approach revealed that the combined abundance of VAV family (VAV2+VAV3) transcripts does show an inverse correlation with the expression levels of both NR2F1 and ZEB2 (red bars) mRNAs in luminal breast tumors." (PMID 30087437, 2019). "Candidates that exhibited the strongest association with breast tumors were regions from the longest introns of RFX2, EPAS1, RBMS1, ZEB2, and the three different introns of CRIM1." (PMID 25798919, 2015). "This study analyzed for the first time the distribution of the two transcripts of ZEB2 directed from distinct promoters in a number of primary breast tumors as well as a number of cell lines." (PMID 25762639, 2015). "The METABRIC database (1904 human breast tumors) consistently revealed a positive association of NME4 with epithelial markers CDH1 and KRT18 and a negative association with mesenchymal markers CDH2 and VIM as well as many EMT drivers like ZEB1, ZEB2, SNAI2, TWIST1, and TWIST2." (PMID 34674701, 2021). "However, when stratified by ZEB2 expression in the breast tumor, patients with high-ZEB2 levels demonstrated significantly lower survival probability than those with low-ZEB2 levels, with a median survival of 4267 days in low-ZEB2 expressors in contrast to 2965 days in high-ZEB2 patients." (PMID 38719798, 2024).
endometrial carcinoma (8 papers, 2014 to 2023). A malignant tumor arising from the epithelium that lines the cavity of the uterine body. "The expression of miR-625 was negatively associated with the expression of ZEB2 in endometrial cancer tissues." (PMID 35992812, 2022). "Taken together, our results constructed a circ_0007534/miR-625/ZEB2 signaling, which drives endometrial cancer progression and chemoresistance by modulating several key EMT-related genes, including Twist1, MMP2, E-cadherin, and Vimentin." (PMID 35992812, 2022). "Collectively, these findings suggested that oncogenic circ_0007534 facilitates EMT, invasion, and Paclitaxel resistance in endometrial cancer through the miR-625/ZEB2 pathway." (PMID 35992812, 2022). "Using a real-time PCR assay, we proved that ZEB2 levels were significantly higher in all endometrial cancer cells than in normal cells." (PMID 35992812, 2022). "This study has shown a possible mechanism that accounts for the aberrant induction of ZEB2 expression in endometrial cancer patients." (PMID 35992812, 2022). "We have revealed that silencing of ZEB2 can effectively make endometrial cancer cells more sensitive to Paclitaxel treatment and lead to the downregulation of Twist1, MMP2, and vimentin and upregulation of E-cadherin." (PMID 35992812, 2022). "In conclusion, circ_0007534 promotes EMT, invasion, and paclitaxel resistance in endometrial cancer via the miR625/ZEB2 pathway." (PMID 36505874, 2022). "Existing research on ZEB2 has shown that it serves as a novel oncogene to accelerate endometrial cancer progression." (PMID 35992812, 2022). "Since ZEB2 is a key EMT activator in endometrial cancer and is possibly involved in chemoresistance in other tumor types, we selected ZEB2 and performed subsequent research." (PMID 35992812, 2022). "Using the dual-luciferase reporter assay, we discovered that miR-625 was a key miRNA that directly binds to ZEB2 mRNA and represses its expression in endometrial cancer cells." (PMID 35992812, 2022). "Multiple miRNAs (including miR-1270 and miR-377) can regulate the levels of ZEB2 in endometrial cancer." (PMID 35992812, 2022). "ZEB2 can trigger EMT in endometrial cancer by raising vimentin levels while decreasing E-cadherin expression." (PMID 35992812, 2022). "In this work, we report an essential function of circ_0007534 in endometrial cancer, in which circ_0007534 acts as a sponge for miR-625 to increase ZEB2 levels, hence promoting EMT and Paclitaxel resistance in endometrial cancer." (PMID 35992812, 2022). "When endometrial cancer cells were transfected with siRNA against ZEB2, the level of ZEB2 was successfully decreased, the level of E-cadherin was increased, and the levels of Twist1, vimentin, and MMP2 were decreased, whereas the overexpression group produced the opposite effect." (PMID 36505874, 2022). "Targeting the circ_0007534/miR-625/ZEB2 pathway might be an effective strategy for overcoming paclitaxel resistance in endometrial cancer." (PMID 35992812, 2022). "Consequently, the present study indicated that the circ_0007534/miR-625/ZEB2 pathway might be a significant therapeutic target for overcoming Paclitaxel resistance in endometrial cancer." (PMID 35992812, 2022). "Therefore, decreasing ZEB2 levels might sensitize refractory endometrial cancer to Paclitaxel." (PMID 35992812, 2022). "In this study, we wondered whether modulation of ZEB2 levels could have an impact on the EMT properties and the sensitivity of endometrial cancer cells to Paclitaxel." (PMID 35992812, 2022).
liver fibrosis (8 papers, 2012 to 2025). "ZEB2, another gene identified in the GWAS, has been suggested to interfere with this apoptosis and has increased expression in liver fibrosis." (PMID 38397136, 2024). "The vascular maintenance and anti-fibrotic role of endothelial Zeb2 was confirmed in mice with EC-specific overexpression of Zeb2, as the latter resulted in reduced vascularity and attenuated CCl4-induced liver fibrosis." (PMID 33909875, 2022). "Here, we aimed to elucidate the endothelium-specific role of Zeb2 during maintenance of the liver and in liver fibrosis." (PMID 33909875, 2022). "Here, we demonstrated that miR-145 and TRAIL were down-regulated in both liver fibrosis tissue samples and transforming growth factor-β1 induced HSCs, concomitant with increased the expression of ZEB2." (PMID 29375381, 2017). "Liver fibrosis cells are more mesenchymal in character, with increased Snail1, Zeb1 and Zeb2 mRNA expression and decreased E-cadherin expression." (PMID 23226767, 2012). "Zeb2 and Zeb2-dependent genes in liver ECs may be exploited to design novel therapeutic strategies to attenuate hepatic fibrosis." (PMID 33909875, 2022). "Here, we studied the role of Zeb2 upon toxin-induced liver fibrosis." (PMID 33909875, 2022). "Endothelial Zeb2 preserves liver angioarchitecture and protects against liver fibrosis." (PMID 33909875, 2022). "Although these studies imply that ZEB2 has an effect on liver fibrosis, the regulation effect of ZEB2 to TRAIL-induced apoptosis of activated HSCs during through NF-κB liver fibrosis remains unclear." (PMID 29375381, 2017). "Correspondingly, we detected the expression of ZEB2 in liver fibrosis tissues." (PMID 29375381, 2017). "Additionally, ZEB2, known for preserving liver angioarchitecture and protecting against liver fibrosis, may also play a role in peritoneal fibrosis." (PMID 38443979, 2024). "Therefore, Zeb2 and Zeb2-dependent genes represent appealing targets to tackle liver fibrosis." (PMID 33909875, 2022). "Collectively, our data suggest that up-regulation of miR-145 can down-regulate ZEB2 expression, consequently promoting TRAIL-induced apoptosis in LX-2 cells through NF-κB signaling pathway, which facilitates the resolution of liver fibrosis." (PMID 29375381, 2017). "Importantly, the double immunofluorescence staining showed that the expression of ZEB2 was primarily co-localized with α-SMA, indicating that HSCs can be considered as one of the main sources of the ZEB2 levels present in liver fibrosis tissues." (PMID 29375381, 2017). "In agreement with the increased liver fibrosis in TCDD-treated TiparpH532A mice, we observed higher gene expression levels of transforming growth factor β (Tgfb), zinc finger E-box binding homeobox 2 (Zeb2) and collagen type I alpha 1 chain (Col1a1), all of which are associated with fibrosis." (PMID 34129049, 2021). "Therefore, miR-145 might down-regulated ZEB2 through NF-κB signaling pathway, which enhanced sensitivity of LX-2 cells to TRAIL-induced apoptosis and subsequent protection against TGF-β1-induced liver fibrosis." (PMID 29375381, 2017).
gastric adenocarcinoma (7 papers, 2012 to 2026). "In addition, Cong N and his colleague found that down-regulated microRNA-200 family was able to promote EMT through wnt/β-catenin pathway by targeting E-cadherin repressors ZEB1/ZEB2 in gastric adenocarcinoma." (PMID 24626466, 2014). "We identified for the first time in gastric adenocarcinoma SGC7901 cells that over-expression of miR-200a reduced levels of ZEB1, ZEB2 and N-cadherin and increase E-cadherin levels." (PMID 22211245, 2012).